TNF (tumor necrosis factor)
Diseases named in the same sentence as TNF in open-access papers (continued):
Sharing a sentence is not in itself a finding about the gene and the disease.
tumor (continued). "It has also been reported that CD53 is linked to tumor necrosis factor-α (TNF-α) expression by genome-wide association analysis, which may change the tumor immunogenic microenvironment and then affect the immune response." (PMID 34856991, 2021). "PD-L1 converts tumor cell apoptosis induced by TNF-α into pyroptosis, resulting in tumor necrosis." (PMID 35280928, 2021). "Therefore, TNF has been used as an active payload for the generation of tumor-specific immunocytokines." (PMID 34576184, 2021). "NK cells work as the effector branch of the innate immune system and undergo activation in response to a reduction or complete abrogation of the self-human leukocyte antigen (HLA-I) alleles on tumor cells, with the release of granzyme and perforin alongside the production of IFN-gamma and TNF alpha." (PMID 34685762, 2021). "CD4+T cells can secrete IFN-γ, IL-2, and TNFα cytokines to interfere with tumor development." (PMID 34804019, 2021). "The upregulated levels of STAU2 protein only in T and B cells might be related to the RNA transport mechanism to produce various inflammatory cytokine (IL-10, TNF-α) molecules that are required to promote tumour growth in the cancer microenvironment." (PMID 33441653, 2021). "The history of TNF-α is closely related to the history of tumor immunotherapy." (PMID 34388989, 2021). "Moreover, this nanomaterial induced not only the activation of both CD4+ and CD8+ T cells in the tumor site but also secretion of anti-cancer-related cytokines such as IL-12 and TNF-α." (PMID 34576180, 2021). "TNFα has been identified as a proinflammatory cytokine that kills tumor cells and microorganisms, but it has also been suggested to lower insulin sensitivity through induction of inflammatory molecules such as MCP1 and IL-6 and through the reduction of adiponectin expression." (PMID 35050148, 2021). "Further investigations are still needed to support the use of PGG in the induction of TNF and its receptors, which might be a helpful strategy to increase tumor sensitivity to chemotherapy." (PMID 33707603, 2021). "Most studies suggest that TNF plays mainly the pro-tumor role in CRC development." (PMID 35008550, 2021). "Additionally, TNF has also been shown to promote tumor growth and metastasis via induction of epithelial-derived oncogene MACC1." (PMID 33435303, 2021). "It was revealed that the main enriched pathways in the tumor, including epithelial-mesenchymal transformation, hypoxia, inflammatory Response, interferon-gamma response, and NFkB-mediated TNFα signal transduction were closely related to the function of CAFs." (PMID 34778248, 2021). "The recruited macrophages could be activated by the MSN-SP-LPS to attack tumor cells directly by secreting tumor necrosis factor-α (TNF-α) or subsequently activating T cells for initiating the antitumor immune response." (PMID 34557478, 2021). "Especially the expansion of metabolically active MDSCs, as immature granulocyte-differentiation antigen 1-positive (GR-1+) CD11b+ cells secreting large amounts of inflammatory cytokines (mainly TNF-α, IL-1, and IL-6), suggests a late development of the CC in the tumor-bearing host." (PMID 33557173, 2021). "In addition, the administration of a fusion protein of TNFα targeting tumor vessels can rescue their normal permeability and promote tumor infiltration by cytotoxic T lymphocytes, enhancing the effectiveness of immune checkpoint inhibitors." (PMID 33540543, 2021). "It plays a role in the cytotoxic ability of these cells that is independent of antibodies as signaling through NKp46 leads to secretion of IFN-γ and TNF-α as well as other inflammatory cytokines that can directly affect tumor cells or ongoing adaptive immune responses." (PMID 34733416, 2021). "Interestingly, the tumor volume was reduced by tamoxifen as well as TNFα treatment or NCOR1 knockdown." (PMID 34073371, 2021).
tumor (continued). "Our results revealed that the TNF‐α‐ or LPS‐simulated inflammatory microenvironment increased DNA resistance to cisplatin and reduced the sensitivity of OS cells to cisplatin, thereby reducing tumour apoptosis and promoting survival." (PMID 34296479, 2021). "Acute and transient inflammation may inhibit tumor growth by upregulating pro-inflammatory cytokines such as TNFα, IL-1β, and IL-6 that are part of the initial inflammatory cascade and recruit other downstream targets to enhance anti-tumor responses." (PMID 34975408, 2021). "When monocytes are stimulated by inflammatory factors, such as interferon-gamma and lipopolysaccharide, they activate M1 macrophages, which can secrete inflammatory factors, such as IL-6 and tumor necrosis factor-alpha, and can phagocytize invasive pathogens and tumor cells." (PMID 33737938, 2021). "Since interferon-gamma (IFNγ) and tumor necrosis factor-alpha (TNFα) in the tumor environment play a vital role in antitumor activity via the stimulation of tumor-specific cytotoxic T cells, cytolytic responses by CTLs were also observed by immunohistochemistry (IHC) staining." (PMID 34389619, 2021). "Confirming TBK1 vs. IKKα/β dichotomy of mRIPO vs. LPS treatment, tumor homogenate cytokine analysis revealed stronger IKKα/β-driven cytokine induction by LPS (IL-6, TNF, IL-1β, IL-10), with CXCL10 (TBK1-dependent) being the most prominently induced cytokine after mRIPO treatment." (PMID 33767151, 2021). "However, NECA-mediated suppressed tumor killing and TNF-α secretion were restored under 1 μM BAY 60-6583 treatment, and anti-CD133 CAR T cells even showed enhanced activity in the presence of higher concentrations of BAY 60-6583." (PMID 33776765, 2021). "Likewise, EA reduced the expressions of IL-1β protein and TNF-α protein and increased the expression of IL-10 protein in tumor tissues." (PMID 35095910, 2021). "Similarly, a high number of tumor-associated macrophages lead to an increased production of angiogenic factors such as VEGF, PDGF, IL-8, TNF-α und bFGF and an enhanced expression of angiogenesis promoting enzymes such as MMP-2, MMP-7, MMP-9 and MMP-12." (PMID 34821752, 2021). "Given that increased TNFα and interferon-γ response represent an activated antimicrobial immune status, we next wondered whether immune infiltration differs between tumor subtypes." (PMID 34465850, 2021). "Surprisingly, when we observed the tumor tissue of each group, the expression of TNF-α in the DTX@H-bMSCs group was significantly higher than that in other groups, which suggests that hypoxia engineering of bMSCs improved the upregulation of inflammatory expression in the TME." (PMID 34069607, 2021). "Helios-deficient tumor-infiltrating Treg cells produced significant amounts of proinflammatory cytokines (TNF-a, IFN-γ), displayed a nonanergic phenotype, reduced immunosuppressive activity and profoundly restrained Foxp3 and CD25 expression." (PMID 34539668, 2021). "APS could upregulate the level of nitric oxide (NO) and tumour necrosis factor‐α (TNF‐α), which acted as inducers of tumour cell apoptosis." (PMID 34302428, 2021). "Additionally, TNF-α is detected in tumor tissue and secreted by malignant tumor tissues or interstitial tumor cells." (PMID 34367136, 2021). "We and others have shown that a short-term stimulation through IL12, IL15, and IL18 receptors induce NK cells with an enhanced ability to produce IFNγ, TNF, and MIP1α in response to cytokines, activating receptors triggering or restimulation with tumor targets." (PMID 34187852, 2021). "As for M1 macrophages, it could suppress tumor growth by both cytophagocytic effects and the production of TNF-α, reactive oxygen species (ROS), and cytokines like IL-1, IL-12, IL-15, and IL-18 to enhance Th1 response." (PMID 34650926, 2021). "Probably, other factors such as cytokine expression of IFN gamma or TNF-alpha may be involved in inducing tumor cell apoptosis." (PMID 33180184, 2021).
tumor (continued). "Alternatively, CD103+CD8+ T cells may have a role in tumor suppression beyond direct cytotoxic killing through the secretion of TNFα and IFNγ, or the recruitment of other immune cell populations that in turn may limit tumor growth." (PMID 33968059, 2021). "Therefore, anti-TNF-a treatment with 5-FU can induce HCC tumor cell apoptosis via antibody-dependent cellular cytotoxicity (ADCC) and complement-dependent cytotoxicity (CDC) processes." (PMID 34948424, 2021). "We removed two consecutive glycine residues in the hinge region to reduce the flexibility of the hinge domain, thus resulting in better tumor control and lower release of inflammatory factors such as TNF-α and IL-6, which are the key molecules triggering the cytokine storm." (PMID 34675920, 2021). "In addition, carboplatin and LyeTx I-b decreased the production of TNF-α in the spleen, which can accumulate tumor-promoting immune cells responsible for the metastatic process." (PMID 34572719, 2021). "However, in a later study, TNFR2 expressed on macrophages was proven to be sufficient to mediate the antitumor effect of TNF-α, probably by the inhibition of tumor angiogenesis." (PMID 34712661, 2021). "Breast cancer infiltrating pDCs have shown an impaired capability to secrete IFN-α, which may be partially explained by the higher concentrations of TGF-β and TNF-α found in the tumor microenvironment." (PMID 34977027, 2021). "Collectively, 30%–40% of splenic LSK cells expressed TNF-α in a tumor-independent manner." (PMID 33936078, 2021). "However, in the tumor microenvironment of cisplatin-treated group, the remaining neutrophils expressed the same level of TNF-α as vehicle-treated group." (PMID 33814009, 2021). "Growing evidence shows that TNF is a key mediator of inflammation and tumour growth." (PMID 33300633, 2021). "Such biochemical and cellular alterations may in turn result in an inflammatory local response potentially mediated by IL-6, IL-1β, and TNF-α, and inhibition of tumor growth." (PMID 34060472, 2021). "Activates macrophages to release TNFα enhancing growth of tumor cells." (PMID 34447383, 2021). "Lowering tumor TNF cytotoxicity threshold can augment the immunotherapy impact." (PMID 33373873, 2021). "Interestingly, TNFα, is also an important inflammatory cytokine, it is a central mediator of inflammation that promotes tumor growth." (PMID 34025421, 2021). "Similarly, TGF-β can also activate the expression of TNF-α in in vitro and in vivo experiments and plays an important role in tissue injury repair, inflammation and tumor growth." (PMID 35069596, 2021). "Systemically, the sustained presence of elevated cytokines that can drive tumor immune surveillance such as IL-1044, GM-CSF, IL-12, and IFNγ was intrinsically associated with early onset and sustained tumor engraftment of highly activated CD8+ T cells, including bifunctional IFNγ and TNFα producers." (PMID 34446712, 2021). "The targeted delivery of TNF to the tumor may considerably increase the local concentration in tumor cells, minimizing TNF doses and consequently decreasing the systemic toxicity." (PMID 33707603, 2021). "Thus, there were significant differences in the production of cytokines IFN-γ, IL-6, and TNF-α between naïve and transfected MSCs on the one hand, and naïve and transfected tumor Huh7.5 cells on the other hand." (PMID 34360889, 2021). "A parallel study showed that tumor progressing genes were downregulated in TNF-α-treated ADSCs." (PMID 33924332, 2021). "In addition, it has been shown that several vascular mediators, such as vascular permeability factor (VPF), which is important in tumor angiogenesis, TNF-α, and others elevate the vascular permeability of tumors." (PMID 33672813, 2021). "Notably, RA alone was shown to inhibit inflammation in H22 tumor-bearing mice by reducing the IL-1β, IL-6, and TNF-α levels and p65 and p-p65 expression." (PMID 34833849, 2021).
tumor (continued). "Its adjuvant properties result from induction of type I interferons and pro-inflammatory cytokines such as interleukin (IL)-6, tumor necrosis factor (TNF), and interleukin (IL)−1β8 thus enabling an improved efficacy of cancer immunotherapy in murine tumor models." (PMID 34006895, 2021). "The proportion of Tregs in splenic CD4+ T cells from cryo-thermal treated mice was decreased compared with that in the tumor-bearing control, but TNF-α supplementation after cryo-thermal therapy increased the proportion of Tregs compared to cryo-thermal therapy alone." (PMID 34576115, 2021). "iNOS dependent anti-tumor TAMs skew the TME towards cytotoxicity through stimulating Th1 responses via secretion of CXCL9 and CXCL10, inducing cytotoxic CD8s through TNFα and IL1β, and direct killing of tumor cells through nitric oxide (NO) and Reactive Oxygen Species (ROS)." (PMID 34222022, 2021). "(b) Lysed tumor cells release a high amounts of cytokines, such as TNF-α." (PMID 33995389, 2021). "In vitro assays showed that TNFα treatment led to dedifferentiation of tumor cells." (PMID 33540543, 2021). "KEGG revealed that these genes were involved in a variety of signaling pathways, including the cytokine-cytokine receptor interaction, the TNF signaling pathway, and the NF-kappa B signaling pathway, while the most noticeable difference genes change involved tumor was the MAPK pathway." (PMID 34630502, 2021). "However, overall, the mean of quantified NF-κB transcriptional activation within tumor cell populations over time demonstrated an increase in bioluminescence in TNFα-treated animals compared to control animals that lasted for approximately 40 min." (PMID 33652682, 2021). "Ganoderma lucidum also reduced the TNF-α level under the inflammatory conditions; inflammation is frequent in some kinds of cancers and is known to facilitate the growth and metastasis of tumor cells." (PMID 34305583, 2021). "Besides VEGF, neutrophils are known to secrete other tumor-promoting factors, including hepatocyte growth factor, interleukin-8 (IL-8), IL-6, and tumor necrosis factor, creating a favorable microenvironment for tumor survival." (PMID 33897913, 2021). "Overall, from the TCGA-LUAD database, survival analysis reflects conflicting trends, with Gehan's assay demonstrating a tumor suppressive phenotype of TNF (P = 0.025) and TNFR2 (P = 0.07), while log-rank's test shows a protumorigenic phenotype for TNFR1 (P = 0.03)." (PMID 33373873, 2021). "In addition, lr-NK cells exhibit poor capacity to produce cytokines (IFN-γ and TNF-α) and kill tumor targets." (PMID 34062821, 2021). "Moreover, while TAMs isolated from TC-1/A9 tumors were stimulated in vitro, and both NO and TNF-α contributed to their cytotoxic effect against tumor cells, TC-1/dB2m TAMs showed a decreased capability for polarization and cytotoxicity." (PMID 34205330, 2021). "We then conducted in vivo blockade experiments of both IFN-α/β and TNF-α in the MC38 tumor model." (PMID 33414378, 2021). "This microRNA was shown to indirectly regulate the expression of several cytokines (IL-5, IL-6, CCL-5, TNF-alpha) that in turn may alter the immune infiltration in the tumor microenvironment." (PMID 33544339, 2021). "Moreover, Y111 increased the cytotoxicity of the expanded Vγ2Vδ2 T cells against various NSCLC-derived tumor cell lines with the releases of granzyme B, IFNγ, and TNFα in vitro." (PMID 34040604, 2021). "TNFα can have additional unwanted effects on anti-tumor immune responses." (PMID 34604096, 2021). "However, biglycan itself indirectly induced Angpt 2 expression in endothelial cells; we propose that TNF-α stimulates tumor angiogenesis via suppression of vascular integrity and increased perfusion as a result of biglycan signaling." (PMID 33966638, 2021). "In addition to scFvs, we have also established Bifidobacterium expressing and secreting INFγ and/or TNFα, which displayed notable anti-tumor effects." (PMID 34204302, 2021).
tumor (continued). "For NK cells, a study showed that APS could promote the transformation of mouse peritoneal macrophages to M1 type under the stimulation of tumor cells and increase the production of TNF-α and NO." (PMID 34721026, 2021). "Here again, the tipping point between pro and anti-tumor TNFα effects relies on its concentration." (PMID 33498483, 2021). "By combining the detection of intracellular CD137 and de novo production of TNF and IFNγ after recognition of naturally-presented tumor antigens, we demonstrate that a larger fraction of tumor-specific and reactive CD8+ TILs can be detected in vitro compared to commonly used assays." (PMID 34707600, 2021). "TNF is a key cytokine that modulates the inflammatory response and may play a role in tumor formation, which can regulate cell survival, proliferation, and cell death, as well as the transcription of proinflammatory cytokines by activating pathways." (PMID 34809619, 2021). "Some of these changes are beneficial when it comes to non-tumor-promoting conditions, e.g., the decrease of VEGF, TGFβ, IL6, CXCL1, CXCL9, IL1β, and M2-macrophage-inducing IL4, as well as the increase of immuno-supportive and M1-associated IL12p70 and TNFα." (PMID 34064000, 2021). "TNF-α also serves as a key regulator of the tumor microenvironment." (PMID 35008199, 2021). "The study aimed at assessing whether curcumin induces apoptosis of RCC and the involvement of AKT/mTOR pathway, the effects of curcumin on TNF-α, IL-6 and IL-8 cytokines, and finally, to understand the role of curcumin in autophagy and tumor-growth in vivo." (PMID 34402718, 2021). "Numerous cytokines, including tumor necrosis factor-alpha, interleukin-1, interleukin-6, and interferon-gamma, released either by tumor cells or by the host as inflammatory reaction to tumor cells, have been postulated to play a role in the etiology of cancer cachexia." (PMID 34055649, 2021). "After diagnosing cancer, patients with malignancies generally avoid the administration of anti-TNFα antibody agents because tumor growth may be enhanced by TNFα suppression." (PMID 33849449, 2021). "Together, tumour cells and stellate cells could activate mast cells in vitro, as was indicated by the mast cell release of TNF-α, thereby promoting tumour cell migration." (PMID 33806468, 2021). "We speculated that the released IFNγ and TNFα could also mediate killing of tumor cells in a cell contact-independent manner." (PMID 32666260, 2021). "PD-L1 switches TNFα-induced apoptosis to pyroptosis in cancer cells, resulting in tumor necrosis." (PMID 35280928, 2021). "Other pathologic factors include the increased levels of inflammatory cytokines such as interleukins (IL-6 and IL-1β) and tumor necrosis factor (TNF-α), both of which contribute to tissue inflammation, tumor invasiveness, and less response to endocrine therapies." (PMID 34122114, 2021). "By interpreting our data in the context of available studies on regulation of tryptophan metabolism in UM, we suggest that the primary mechanism is more likely to IFN-γ- and TNF-α-dependent, both of which are produced by tumor-infiltrating cytotoxic lymphocytes." (PMID 34195299, 2021). "The cytokines secreted by mesenchymal stem cells in the bone microenvironment, including TGFβ and tumor necrosis factor α (TNFα), can inhibit lymphocyte proliferation and block the response of the immune system, allowing the tumor to escape the inflammatory response." (PMID 33809018, 2021). "Furthermore, hMSC treatment promoted HCC progression, increased IL-6 and TNF-α expression, and decreased the number of natural killer (NK) cells in tumor niches." (PMID 33849537, 2021). "It revealed that adhesion molecules and their ligands on endothelial cells and tumor cells induced by TNF-α might promote tumor adhesion." (PMID 34222020, 2021).